SSTR2 (somatostatin receptor 2)
Diseases named in the same sentence as SSTR2 in open-access papers (continued):
Sharing a sentence is not in itself a finding about the gene and the disease.
rectal NETs (1 paper, 2024). "SSTR2 expression was significantly associated with favorable behavior and good overall survival in patients with rectal NETs." (PMID 38374188, 2024). "SSTR2 expression were significantly associated with favorable behavior and good overall survival in patients with rectal NETs." (PMID 38374188, 2024). "SSTR2 expression was observed in 234 (66.9%) rectal NET cases and associated tumors with smaller size (p = 0.001), low pT classification (p = 0.030), low AJCC tumor stage (p = 0.012), and absence of chromogranin expression (p = 0.009)." (PMID 38374188, 2024). "In addition, SSTR2 expression was significantly associated with favorable survival and an independent good prognostic factor in rectal NET patients." (PMID 38374188, 2024). "In this study, we evaluated SSTR2 immunohistochemical expression in rectal NETs and correlated with clinicopathologic factors, including patients’ survival." (PMID 38374188, 2024). "SSTR2 expression (p = 0.014), low tumor grade (p = 0.002), and absence of distant metastasis (p < 0.001) were an independent prognostic factors in rectal NET patients." (PMID 38374188, 2024). "Subgroup analysis based on tumor grade showed that grade 1 rectal NET patients with SSTR2 expression had significant better overall survival than those without SSTR2 expression (5-year survival rate, 98.4% vs. 93.4%, p = 0.011)." (PMID 38374188, 2024). "SSTR2 immunohistochemical expressions were evaluated in 350 surgically or endoscopically resected rectal NETs and compared to clinicopathologic factors." (PMID 38374188, 2024). "In conclusion, approximately two-thirds of rectal NETs expressed SSTR2." (PMID 38374188, 2024). "In contrast, SSTR2 expression was observed in 234 (66.9%) rectal NETs." (PMID 38374188, 2024). "Previously reported prevalence of SSTR2 expression in rectal NETs is variable." (PMID 38374188, 2024). "The proportion of SSTR2 expression in rectal NETs ranged from 14 to 100% in the previous studies." (PMID 38374188, 2024). "In summary, approximately two-thirds of rectal NETs expressed SSTR2." (PMID 38374188, 2024). "The low prevalence of SSTR2 expression in previous study may be due to different proportion of high grade (grade 2 and 3) rectal NETs." (PMID 38374188, 2024). "SSTR2 expression was identified in approximately 70% of rectal NETs in the present study." (PMID 38374188, 2024). "However, the association of SSTR2 expression status with clinicopathologic significances in rectal NETs with a large cohort has not been evaluated." (PMID 38374188, 2024). "The 5-year survival rate of rectal NET patients with SSTR2 expression was significantly better than those without SSTR2 expression (98.5% vs. 92.6%, p = 0.006)." (PMID 38374188, 2024). "Patients with rectal NET and SSTR2 expression had significantly better overall survival than those without SSTR2 expression both by univariable (p = 0.006) and multivariable (p = 0.014) analyses." (PMID 38374188, 2024). "The overall survival of rectal NET patients with SSTR2 expression was significantly better than those without SSTR2 expression [hazard ration (HR) 0.346; 95% confidential interval (CI) 0.157–0.759; p = 0.006]." (PMID 38374188, 2024). "SSTR2 expression has previously been reported in GEP NETs, but it has not been specifically reported in rectal NETs." (PMID 38374188, 2024).
renal cell carcinoma (1 paper, 2022). "But other tumor types, such as renal cell carcinoma (RCC), lymphoma, and inactive adenoma, have less SSTR2 or other SSTR subtypes." (PMID 36465350, 2022).
salivary gland tumors (1 paper, 2023). "In this monocentric retrospective study, we examined the somatostatin receptor 2 (SSTR2) status of salivary gland tumors after salivary gland tumor resection via immunohistochemistry (IHC), and stains were compared in analogy to the HER2 mamma scale." (PMID 37568733, 2023). "This sample is the largest described immunohistochemistry examination of SSTR2 in salivary gland tumors." (PMID 37568733, 2023). "Furthermore, the SSTR2 may allow a reliable distinction between the two most common salivary gland tumors, the Warthin tumor and the PA." (PMID 37568733, 2023).
skull base meningioma (1 paper, 2023). A meningioma that arises from the skull base. "In particular, SSTR2 are usually overexpressed among skull base meningiomas." (PMID 37111596, 2023).
Sleep disturbance (1 paper, 2022). An abnormal pattern in the quality, quantity, or characteristics of sleep. "Speculatively, our findings regarding SSTR2 expression and sleep disturbances in subjects with SUD may contribute to impaired consolidation of contextual reward memories that can promote relapse." (PMID 36161151, 2022).
squamous cell carcinoma (1 paper, 2022). A carcinoma arising from squamous epithelial cells. "“Increased uptake” was reported in an additional squamous cell carcinoma which had 0% of tumor cell staining with SSTR2." (PMID 35198446, 2022).
status epilepticus (1 paper, 2020). Status epilepticus is defined as a continuous seizure lasting more than 30 min, or two or more seizures without full recovery of consciousness between any of them. "In line with the claustrum discussion above, SSTR2 activation can inhibit glutamate release and prevent status epilepticus supporting the inhibitory impact of this receptor on salience development to sensory inputs." (PMID 31172348, 2020).
Telangiectasia (1 paper, 2023). Telangiectasias refer to small dilated blood vessels located near the surface of the skin or mucous membranes, measuring between 0.5 and 1 millimeter in diameter. "Significant expression changes existed also for genes responsible for the pathogenesis of telangiectasia (upregulation of Sst, Sstr1, Sstr2, Tac1, Tacr1, Svbp), and for general growth (Sst, Sstr1, Sstr2)." (PMID 37830614, 2023).
temporal arteritis (1 paper, 2024). A large vessel vasculitis predominantly involving the arteries originating from the aortic arch and especially the extracranial branches of the carotid arteries. "While many studies associated SSTR2 expression with endothelial cells, only recent studies have found pericytes associated with SSTR2; for instance, SSTR2 has been related to active inflammation in temporal arteritis and was mainly detected in macrophages and pericytes." (PMID 39767203, 2024).
temporal lobe epilepsy (1 paper, 2011). A localization-related (focal) form of epilepsy characterized by recurrent seizures that arise from foci within the temporal lobe, most commonly from its mesial aspect. "In humans there are five SSTR genes and SSTR2 was found to be downregulated in CA1 and CA3 hippocampal explants surgically obtained from patients with temporal lobe epilepsy, probably reflecting increased neural cell loss in these areas and also the SSTR2 involvement in antiepileptic processes." (PMID 22022585, 2011).
thymic carcinoma (1 paper, 2022). Thymic carcinoma (TC) is a type of thymic epithelial neoplasm characterized by a high malignant potential. "In slightly more than half of thymic carcinomas and TNETs SSTR2 was expressed in 50% or more tumor cells." (PMID 35198446, 2022). "Unfortunately, we were not able to compare the expression of SSTR2 between low and high stage for thymic carcinomas and TNETs separately due to the relative low number of cases." (PMID 35198446, 2022).
thymic tumors (1 paper, 2024). "SSTR2 is also the one most predominantly expressed in thymic tumors." (PMID 39329930, 2024). "The importance of SSTRs in thymic tumors is still a matter of debate, as there is a difference between in vitro cultured cells and in vivo thymomas; SSTR3 seems to be the only one expressed in both cases, while SSTR1 and SSTR2 were detected only in vivo." (PMID 39329930, 2024).
triple-negative breast carcinoma (1 paper, 2026). An invasive breast carcinoma which is negative for expression of estrogen receptor (ER), progesterone receptor (PR), and human epidermal growth factor receptor 2 (HER2). "The goal of this study is to evaluate the effects of HDAC inhibitors and IMT on macrophages, their expression of SSTR2, and their impact on the treatment response in triple-negative breast cancer (TNBC)." (PMID 42198232, 2026).
Warthin tumor (1 paper, 2023). An adenoma characterized by an oncocytic, often papillary, epithelial component, dense lymphoid stroma, and cystic spaces. "All Warthin tumors examined in this study showed an SSTR2 cell count below 20%." (PMID 37568733, 2023). "Different statistical methods were applied in order to investigate whether a combination of the information on the percentage of SSTR2-expressing cells and the signal intensity could be used to increase the discrimination between pleomorphic adenoma and Warthin tumors." (PMID 37568733, 2023).
α-thalassemia (1 paper, 2025).
tumor (377 papers, 1999 to 2026). "A lower SSTR1 and SSTR2 expression levels was associated to primary tumours compared to recurrent GBMs in the TCGA/Murat-cohorts." (PMID 40268793, 2025). "PNET grade inversely correlates with SSTR2 tumor staining and higher tumor grade is associated with poor patient prognosis." (PMID 41040380, 2025). "SSTR2 expression was significantly associated with small tumor size (p = 0.001), low pT classification (p = 0.030), low AJCC stage (p = 0.012), and absence of chromogranin expression (p = 0.009)." (PMID 38374188, 2024). "This study investigates the association of SSTR2 expression with genomic features, immune biomarkers, and the tumor immune microenvironment in a cohort of patients with sinonasal malignancies." (PMID 39682120, 2024). "The association between the tumor microenvironment (TME) with somatostatin receptor 2 (SSTR2) and hypoxia-induced factor-2α (HIF-2α) in PPGLs, critical for optimizing combination therapeutic strategies with immunotherapy, remains largely unexplored." (PMID 38927897, 2024). "FAP was expressed mainly on cancer-associated fibroblasts within the tumor stroma, whereas SSTR2 was expressed predominantly on tumor cells." (PMID 38176714, 2024). "Immunohistochemical analyses conducted on large cohorts of tumor samples observed higher SSTR2 expression in differentiated and low- and intermediate-risk NB than in HR-NB." (PMID 39324010, 2024). "Since radiolabeled TATE variants act as SSTR2 agonists, effective retention in tumor cells initially depends on a high proportion of binding-induced endocytosis of the ligand-receptor-complex." (PMID 39310112, 2024). "We studied SSTR2 gene expression and its association with genomic features, immune biomarkers, and tumor immune microenvironment composition in a cohort of ONB, SNEC, and SNUC." (PMID 39682120, 2024). "Regarding any multimodal treatment, it is important to emphasize that the histopathological workup of pNETs should include essential prognostic (tumor stage, grade, nodal involvement) and predictive factors (SSTR2 status) to guide a risk stratification." (PMID 35326628, 2022). "SSTR2 expression in ≥50% of tumor cells (vs 1-49%) was associated with younger age (p=0.023) and shorter recurrence/metastasis-free survival (p=0.007)." (PMID 35198446, 2022). "At present, few studies have shown that tumor SSTR2 expression status can be associated with clinical outcome, and a more recent study has addressed the correlation between SSTR2 levels and DNA double-strand break (DSB) formation at a preclinical level." (PMID 33837068, 2022). "[213Bi]Bi-3p-C-NETA-TATE and [177Lu]Lu-3p-C-NETA-TATE will be evaluated as potential therapeutic partners for NETs in a theranostic setting in combination with [18F]AlF-3p-C-NETA-TATE as the diagnostic partner using SSTR2 overexpressing mouse tumor models." (PMID 35966589, 2022). "When the 177Lu radiolabeled somatostatin analogue 177Lu-DOTATATE binds to SSTR2 on tumor cells, the complex is internalized, causing ionizing radiation, DNA damage, and, eventually, cell death." (PMID 36551599, 2022). "Somatostatin analogs have been shown to inhibit tumor hypersecretion of peptides and slow tumor growth in gastrointestinal cancers, including NETs, and expression of SSTR2 has been associated with improved survival in patients with gastropancreatic NETs." (PMID 35058882, 2021). "Conversely, SSTR2 expression, which is generally increased in well-differentiated tumors, would be expected to be inversely associated with tumor heterogeneity." (PMID 34408979, 2021). "Compared with the studies above, the present study included only a minority of tumor samples with low SSTR2 expression, possibly introducing a risk of skewed results." (PMID 33922482, 2021). "The 111In-labelled somatostatin analogue, octreotide and the more recently developed 68Ga-labelled analogues have been used widely for diagnostic imaging of SSTR2-expressing tumours by SPECT and PET, respectively." (PMID 32576907, 2020).
tumor (continued). "On the other hand, some studies demonstrate variations on SSTR2 distribution on tumor and normal specimens and these associations with histological grade, proliferation, and treatment of tumors." (PMID 19365586, 2009). "Using mice expressing KrasG12D in pancreatic precursor cells (KC), mice with monoallelic loss of Sstr2 (Sstr2+/–), and crossed KrasG12D/Sstr2+/- mice, this group in more mechanistic detail analysed the effects of Sstr2 loss on tumor growth in the course of Kras-induced PDAC development." (PMID 40134804, 2025). "Similarly, mRNA for the somatostatin receptors, SSTR1 (P < 0.01) and SSTR2 (P < 0.001), which are associated with somatostatin analogue therapy, were differentially expressed across all tumor samples." (PMID 40217502, 2025). "SSTR2 expression is a well-known predictor of favorable outcomes after fgSRL therapy, primarily because these agents exert their effects on reducing GH production and causing tumor shrinkage through preferential binding on this SSTR subtype." (PMID 39201352, 2024). "SSTR2 is the main mediator of SS’s antiproliferative effects on normal and cancer cells and has been an intense target for the development of therapeutic, diagnostic, and theranostic agents for various neoplasms and cancers." (PMID 39164229, 2024). "The tumours causing GH excess expressed both SSTR2 and SSTR5." (PMID 37851558, 2023). "Interestingly, SSTR2 expression is associated with tumour stage, type, localization and most importantly, with the presence of carcinoembryonic antigen in serum." (PMID 38203605, 2023). "Furthermore, the loss of SSTR2 reduced tumor growth in a mouse xenograft model implanted with H1048 human SCLC cells." (PMID 35628495, 2022). "SSTR2 expression in ≥ 50% of tumor cells was associated with worse RFS with an estimated 5-year RFS of 11.4% (95% CI: 0%-32.5%) vs 72.7% (95% CI: 46.4%-99.0%) in patients with 1-49% of tumor cells expressing SSTR2 (p=0.007)." (PMID 35198446, 2022). "In conclusion, we report that the promoter methylation of SSTR2 gene is initiated in normal gastric gland in association with aging and H. pylori infection and that SSTR2 silencing promotes the establishment of inflammatory microenvironment and tumor formation." (PMID 36551669, 2022). "Furthermore, SSTR2 activation can cause tumor cell arrest by upregulating the cyclin dependent kinase inhibitor, p27, by a mechanism involving SHP-1 activation." (PMID 34680266, 2021). "Overall, our results suggested that the GNAS relaxation and loss of A/B DMR methylation could be one of the steps in the dedifferentiation drift including a loss of GNAS, AIP and SSTR2 expression that may contribute to the tumor promotion." (PMID 34299200, 2021). "All observations have indicated that SSTR2 expression and distribution in cancer prostate epithelium cells are stronger and could cause an abnormal response of tumor at somatostatin analogs treatment." (PMID 19365586, 2009). "Similarly, in SCLC, SSTR2 signaling has been linked to tumor progression, suggesting that SSTR2 may exhibit both oncogenic and tumor suppressor functions depending on the cancer type." (PMID 41002582, 2025). "However, the association between SSTR2 expression profiles in tumor cells and the therapeutic efficacy of SSAs remains virtually unknown in GI-NETs, especially in foregut and hindgut NETs." (PMID 35159042, 2022). "Despite SSTR2/5 positivity, suboptimal response to octreotide suggests tumor heterogeneity or downstream signaling defects." (PMID 41625237, 2026). "Many studies primarily focus on adaptive immune cells and their expression of pro-inflammatory markers, like somatostatin receptor 2 (SSTR2); however, macrophages are known to help mediate key tumor microenvironment changes." (PMID 42198232, 2026). "SSTR2 has been found to exhibit anti-tumor properties, however, its expression is lost in most human PDACs, suggesting transcriptional silencing as the underlying mechanism." (PMID 40134804, 2025).